MFN2 (mitofusin 2)
Diseases named in the same sentence as MFN2 in open-access papers (continued):
Sharing a sentence is not in itself a finding about the gene and the disease.
Lipoatrophy (1 paper, 2022). Localized loss of fat tissue. "As an example, MFN2 encoding mitofusin 2 has been involved in the lipodystrophic Launois-Bensaude syndrome, and SLC25A24 encoding a calcium-binding mitochondrial carrier protein has been involved in a complex progeroid syndrome with lipoatrophy." (PMID 35341481, 2022).
lymphoma (1 paper, 2015). A malignant (clonal) proliferation of B- lymphocytes or T- lymphocytes which involves the lymph nodes, bone marrow and/or extranodal sites. "However, in contrast to our finding that down-regulation of Mfn2 repressed cell proliferation, a recent paper reported that Mfn2-null mouse embryonic fibroblast (MEF) and a Mfn2 knockdown clone of lymphoma cell line BJAB displayed increased cell proliferation through Ras-Raf-ERK pathway." (PMID 25781899, 2015).
manic episodes (1 paper, 2017). "However, we found a negative correlation between Mfn2 levels and YMRS (rho=−0.554, P=0.001) and MADRS (rho=−0.426, P=0.019) scores, as well as with the number of manic episodes (rho=−0.551, P=0.035)." (PMID 28463235, 2017).
mesothelioma (1 paper, 2016). A usually malignant and aggressive neoplasm of the mesothelium which is often associated with exposure to asbestos. "There was a decrease in total DRP1 and MFN2 in mesothelioma cell lines compared to the MeT-5A mesothelium control cells, suggestive of decreased fission/fusion cycling in these cells." (PMID 27080907, 2016). "Similarly to the trend observed in total cell lysates, DRP1 levels were increased relative to MFN2 in mitochondrial fraction of the mesothelioma cells lines." (PMID 27080907, 2016). "However there was also a shift in the relative levels of these proteins in the mesothelioma cell lines towards higher expression of the fission regulator DRP1 compared to MFN2, the fusion regulator." (PMID 27080907, 2016).
Miscarriage (1 paper, 2023). A pregnancy that ends at a stage in which the fetus is incapable of surviving on its own, defined as the spontaneous loss of a fetus before the 22th week of pregnancy. "As MFN2 deficiency causes the accumulation of damaged mitochondria by the failure of autophagy and impaired metabolic homeostasis by reactive oxygen species, the downregulation of MFN2 might be related to a defect in syncytialization, which leads to miscarriage." (PMID 36979065, 2023).
Motor axonal neuropathy (1 paper, 2024). Progressive impairment of function of motor axons with muscle weakness, atrophy, and cramps. "Patients with MFN2-associated MSL exhibit a Charcot–Marie–Tooth neuropathy, which manifests as a four-limb peripheral sensitive-motor axonal neuropathy of early onset." (PMID 39113684, 2024).
motor neuron disease (1 paper, 2024). "Further research is needed to understand whether MFN2 mutations contribute to motor neuron disease and to what extent." (PMID 39315308, 2024).
mtDNA depletion syndromes (1 paper, 2019). "Importantly, the degree of mtDNA depletion we see in MSTO1 patient fibroblasts (30–70% of the normal content) is consistent with the levels of mtDNA depletion reported in fibroblasts from OPA1 or MFN2 patients as well as in mtDNA depletion syndromes." (PMID 31463572, 2019).
myocardial disease (1 paper, 2023). "First, we provide plausible evidence for a contribution of impaired MFN2-Parkin-mediated mitophagy to myocardial disease." (PMID 37910431, 2023).
Myocardial fibrosis (1 paper, 2023). "However, Mfn2 deficiency has been shown to impair cardiac function, cause heightened myocardial fibrosis, increase mitochondrial damage, and worsen oxidative stress." (PMID 37304955, 2023).
myocarditis (1 paper, 2023). Myocarditis is a condition that is characterized by inflammation of the heart muscle (myocardium). "Second, we confirmed that mTOR, GSK3β, PTPN11 and MFN2 are highly expressed in ICI-related myocarditis by proteomic sequencing, cellular experiments are required to verify our hypothesis." (PMID 36760573, 2023). "By combining PD-L1-related proteins, we found that mTOR, GSK3β, PTPN11, and MFN2 may be potential diagnosis and treatment biomarkers of ICI-associated myocarditis." (PMID 36760573, 2023). "By analyzing coexpressed proteins, we found four hub proteins that may lead to the occurrence of ICI-related myocarditis, mammalian target of rapamycin (mTOR), GSK3β, PTPN11, and MFN2." (PMID 36760573, 2023).
myopia (1 paper, 2025). "EA treatment might regulate lncRNA-XR_002789763.1/miR-342-5p axis and activate the mitophagy-related PINK1/Parkin signaling pathway, and promote Mfn2 ubiquitination, thereby alleviating RGC damage and delaying myopia progression in guinea pigs." (PMID 39894836, 2025). "EA treatment might regulate lncRNA-XR_002789763.1/miR-342-5p axis and activate the mitophagy-related PINK1/Parkin signaling pathway, and promote Mfn2 ubiquitination, thereby alleviating RGC damage and delaying myopia progression." (PMID 39894836, 2025).
non-small cell lung carcinoma (1 paper, 2020). A group of at least three distinct histological types of lung cancer, including non-small cell squamous cell carcinoma, adenocarcinoma, and large cell carcinoma. "In non-small cell lung cancer (NSCLC) cells, AIM2 colocalizes with mitochondria, where it regulates mitofusin 2 expression and mitochondrial fusion." (PMID 32906750, 2020).
normal tension glaucoma (1 paper, 2009). "Common variants of OPTN, PARL, MFN1 and MFN2 should be analysed in other cohorts to confirm their involvement in normal tension glaucoma." (PMID 19754948, 2009).
oncocytic tumors (1 paper, 2025). "Notably, MFN2, OPA1, DRP1, and FIS1 have been found to be overexpressed in oncocytic tumors, independent of mitochondrial content." (PMID 40485730, 2025).
optic atrophy type 1 (1 paper, 2022). "The dynamics of mitochondrial morphology are mediated by mitofusin-1(Mfn1), Mfn2, and optic atrophy type 1." (PMID 36212689, 2022).
periodontal disease (1 paper, 2025). "The current comprehensive review shows the important roles of MFN1 along with MFN2 in inflammation regulation, cell survival, and mitochondrial dynamics within periodontal disease." (PMID 39896143, 2025). "The included studies in this review provide a comprehensive look at the roles of MFN1 and MFN2 in periodontal disease, utilizing a variety of models, including in vitro and in vivo approaches." (PMID 39896143, 2025). "MFN1 along MFN2 are both important for managing oxidative stress, this is a crucial grantor to the evolution of periodontal disease." (PMID 39896143, 2025). "Periodontal disease is an inflammatory disease where a disparity of calcium, as well as apoptosis in cells, can exacerbate tissue damage, and MFN2's function in controlling ER-mitochondria transmission becomes more important." (PMID 39896143, 2025). "Key findings indicate that MFN1 and MFN2 levels are often reduced in periodontal disease conditions, correlating with increased oxidative stress, inflammation, and mitochondrial dysfunction." (PMID 39896143, 2025). "In conclusion, this comprehensive review highlights the critical roles of MFN1 and MFN2 in mitochondrial dynamics, inflammation regulation, and cell survival within periodontal disease." (PMID 39896143, 2025). "It is considered that MFN2 can decrease tissue damage in periodontal disease, controlling the MAPK and NF-κB signaling pathways including regulating cytokine release, as a result dampening the inflammatory response." (PMID 39896143, 2025). "The included studies underscore the significant role that MFN1 and MFN2 play in mitochondrial dynamics and their implications in periodontal disease." (PMID 39896143, 2025). "MFN1 and MFN2 levels were monitored in order to shed light on the possible role of mitochondria-endoplasmic reticulum interaction genes in the etiology of periodontal disease." (PMID 39896143, 2025). "The therapeutic possibility of targeting MFN1 along MFN2 for periodontal disease is ascribed to their purpose in mitochondrial fusion, control of inflammation, and cellular resilience." (PMID 39896143, 2025). "The study of MFN1 along with MFN2 as a therapeutic quarry, offers a promising perception of periodontal disease care." (PMID 39896143, 2025). "This comprehensive review aims to evaluate the part of MFN1 along MFN2 in the pathogenesis, including the progression of periodontal disease, focusing their effect on oxidative stress, inflammatory pathways, and mitochondrial integrity." (PMID 39896143, 2025). "MFN1 among MFN2 significantly mitigates oxidative stress as well as inflammation and is censorious in periodontal disease." (PMID 39896143, 2025). "MFN1 along with MFN2 modulates inflammatory signaling and controls ROS generation, so influencing the host immunological reaction to pathogens and may influence the course of periodontal disease and severity." (PMID 39896143, 2025). "Speaking about how MFN1 along MFN2 work in periodontal disease could give new intuition into pathogenesis as well as possible treatment approaches as they are important for preserving cellular stress, regulating inflammatory pathways, and mitochondrial integrity." (PMID 39896143, 2025). "Their cooperative participation in fusion, together with MFN2's extra roles in cellular signaling and apoptotic control, emphasizes their relevance in disease processes when oxidative stress, mitochondrial malfunction, and inflammation are clearly present, as in periodontal disease." (PMID 39896143, 2025). "In conditions such as periodontal disease, oxidative stress, and inflammation are frequent, MFN1 along MFN2 assist in preventing cell damage by managing mitochondrial integrity." (PMID 39896143, 2025). "Studies were selected depending on inclusion criteria based on the roles of MFN2 and MFN1 in periodontal disease and health." (PMID 39896143, 2025).
periodontal disease (continued). "The purpose of MFN1, along with MFN2 encompasses not just mitochondrial integrity and the regulation of inflammation, a crucial element in periodontal disease." (PMID 39896143, 2025). "The aim of the current study is to comprehensively review including evaluate the roles of MFN2 and MFN1 in the pathogenesis as well as the progression of periodontal disease, foregrounding their effect on mitochondrial integrity, inflammatory pathways, and oxidative stress." (PMID 39896143, 2025).
pneumoconiosis (1 paper, 2026). An occupational lung disorder caused by inhalation of dust particles. "This study highlights the importance of the MFN2-MAMs-Ca2+-apoptosis axis and identifies MFN2 as a potential therapeutic target for pneumoconiosis." (PMID 42198516, 2026).
prostatitis (1 paper, 2023). An infectious or non-infectious inflammatory process affecting the prostate gland. "Further study with a larger sample size may be necessary to elucidate the real role of Drp-1 and MFN-2 in a CAR-induced prostatitis model in rats." (PMID 36835316, 2023).
proteopathy (1 paper, 2022). "Proteopathy- associated regions have higher proportions of MFN2(+) neurons relative to non-proteopathy associated regions in the CN hippocampus." (PMID 36333818, 2022). "Neuronal MFN2 expression was positive primarily in non-proteopathy associated neurons, with a clear overlap in proteopathy associated neurons." (PMID 36333818, 2022). "Given the role of neuron-mitochondrial dysfunction found in multiple models of AD, MFN2 may represent an important target for maintaining survival in proteopathy-susceptible neuron populations." (PMID 36333818, 2022). "These MFN2 positive neurons were more prevalent in proteopathy-associated regions (MD, AP, TT) relative to the non-proteopathy associated regions (ND, GD), suggesting that MFN2 expression may be associated with neuronal survival in the presence of stressors from proteopathy." (PMID 36333818, 2022). "Additionally, in the ADD sample the percentage of MFN2(+) neurons in the non-proteopathy associated regions has jumped up considerably relative to the CN sample, further suggesting that this MFN2(+) expression may indicate an association with protection from the spread of proteopathy." (PMID 36333818, 2022). "To understand MFN2-related persistence in proteopathy-laden regions, we compared the single-cell relationship between proteopathy expression and MFN2." (PMID 36333818, 2022). "As MFN2 was variably expressed across multiple non-proteopathy associated (clusters 3, 4) and proteopathy-associated neuronal clusters (clusters 1, 2, 10), we further investigated its expression and localization in the hippocampus." (PMID 36333818, 2022). "Importantly, we also found a prevalence of MFN2 expression in proteopathy-burdened hippocampal regions, particularly in areas of pathologic Tau." (PMID 36333818, 2022).
renal carcinoma (1 paper, 2023). A carcinoma arising from the epithelium of the renal parenchyma or the renal pelvis. "We investigated the role of MFN2 in renal cancer cells using CCK 8, clone formation, wound healing assay, and methylase qPCR experiments." (PMID 37845657, 2023).
retinal diseases (1 paper, 2014). "Accordingly, rescue of Mfn2 loss and modulation of O-GlcNAcylation might represent potential novel therapeutic avenues for the treatment of aging-related retinal diseases." (PMID 24987494, 2014).
scrapie (1 paper, 2023). A fatal disease of the nervous system in sheep and goats, characterized by pruritus, debility, and locomotor incoordination. "In scrapie-infected mice, an imbalance in mitochondrial fusion and fission proteins such as Mfn1, Fis1, Mfn2, and Dlp1 was observed." (PMID 37569615, 2023).
Seizure (1 paper, 2024). A seizure is an intermittent abnormality of nervous system physiology characterized by a transient occurrence of signs and/or symptoms due to abnormal excessive or synchronous neuronal activity in the brain. "A recent study showed that the expression level of Mfn2 was significantly decreased in the hippocampal tissues of a rat model of lithium–pilocarpine-induced epileptic seizure." (PMID 39457518, 2024).
Sensory neuropathy (1 paper, 2018). Peripheral neuropathy affecting the sensory nerves. "Indeed, loss of function of mitochondrial proteins such as bcl-w or mitofusin-2 results in a length-dependent dying-back sensory neuropathy." (PMID 29997469, 2018).
spinal cord injury (1 paper, 2024). Penetrating and non-penetrating injuries to the spinal cord resulting from traumatic external forces (e.g., WOUNDS, GUNSHOT; WHIPLASH INJURIES; etc.). "Downregulation of mitofusin (Mfn2) expression in microglial cells induces the release of mtDNA, which in turn mediates the activation of stimulator of interferon genes (Sting) and aggravates the inflammatory response damage after spinal cord injury (SCI)." (PMID 38009491, 2024).
thyroid tumor (1 paper, 2015). A benign or malignant neoplasm affecting the thyroid gland. "The expression of mitochondrial fusion (Opa1, Mfn1 and Mfn2) and fission (Drp1 and Fis1) proteins were evaluated by immunohistochemistry (IHC) in a series of 88 human thyroid tumors." (PMID 25822260, 2015).
triple-negative breast carcinoma (1 paper, 2021). An invasive breast carcinoma which is negative for expression of estrogen receptor (ER), progesterone receptor (PR), and human epidermal growth factor receptor 2 (HER2). "In triple negative breast cancers, mitofusin-2 is a catalyst of mitochondrial fusion, which results in cell cycle arrest and the inhibition of cell proliferation." (PMID 33924764, 2021).
cancer (96 papers, 2013 to 2026). A tumor composed of atypical neoplastic, often pleomorphic cells that invade other tissues. "Conversely, the fusion protein MFN2 has been implicated in regulating angiogenesis and metastasis in cancers; notably, MFN2 overexpression in endothelial cells suppresses angiogenesis by downregulating proangiogenic factors." (PMID 40979213, 2025). "As examples, we experimentally validated three rare variants in cancer-associated genes (MFN2, FOSL2, and IRAK1), confirming their functional roles in regulating mRNA stability and cell proliferation." (PMID 38637555, 2024). "Through prime editing, we characterized three variants in cancer-relevant genes (MFN2, FOSL2, and IRAK1), demonstrating their cancer-driving potential." (PMID 38637555, 2024). "PI3K pathway is a well-known downstream signaling pathway in RAS mutated cancer cells and there was a positive correlation of MFN2 mRNA expression and RAS like gene expression in our data." (PMID 33479369, 2021). "In studies that analyzed the MFN2 mRNA and protein levels in human tissues in various types of cancer, the expression of MFN2 was found to be negatively associated with cancer progression." (PMID 33479369, 2021). "The pathways enriched were mainly related to viral carcinogenesis by DAIVD, which indicated that Mfn2 is closely linked to the pathogenesis of cancer." (PMID 30046371, 2018). "Higher expression of Mfn1 and Mfn2 has been linked with cancer cell proliferation, enhanced cell survival and invasion." (PMID 28473727, 2017). "Collectively, this study provides novel insights into the tumor progression associated with MFN2 deficiency and suggests that the importance of mTORC2 inhibitor in the treatment of MFN2 downregulated cancer patients." (PMID 28176801, 2017). "Mfn2 promotes anti-proliferative and pro-apoptotic effects via PI3K–AKT signalling pathway and lower expression of Mfn2 is associated with poor survival in cancer." (PMID 28373964, 2017). "Clinical and epidemiological evidence revealed that low MFN2 expression in many types of cancer is associated with poor prognosis." (PMID 28176801, 2017). "Another study confirmed the antitumor activity of an adenoviral vector encoding human Mfn2 (designated Ad5-hHSG) in a variety of cancer cell lines." (PMID 25120590, 2014). "MFN2 dysregulation is associated with various diseases, such as atherosclerosis, Charcot–Marie–Tooth disease, male infertility, obesity, hypertension, diabetes, and cancer." (PMID 36877954, 2023). "In addition, MFN2 has been implicated in the regulation of metabolism in cancer cells and shown to interact with PKM2." (PMID 35846359, 2022). "EMT-associated protein expression was induced after MFN2 KO in both cancer cell lines." (PMID 33479369, 2021). "The expression of MFN2 has been shown by other groups to be implicated in various cancers." (PMID 30932749, 2019). "Multiple studies have demonstrated that enhanced fission or reduced fusion, high expression or enhanced activation of Drp1, and/or downregulation of MFN2 are linked to several cancer-related phenotypes, indicating that cancer cells often exhibit fragmented mitochondria." (PMID 30691497, 2019). "Indeed in gastric cancers, a cancer that can harbor Ras mutations, there is decreased Mfn2 expression, suggesting possible selective pressure against the sequestration and inhibition of a mitogenic signal." (PMID 28513539, 2017). "Indeed, and consistent with a role of mitofusin-2 as a MAM promoter, cancer cells with high levels of mitofusin-2 are more susceptible for apoptosis and more competent for ER–mitochondria Ca2+ flux." (PMID 28603693, 2017). "While Ras and Raf are implicated in these, especially where Mfn2 is concerned, our results indicate there could be another pathway involving mitochondrial superoxide by which cancer cells could up-regulate cyclin B and hyperproliferate." (PMID 26000631, 2015).